CHEK1 (checkpoint kinase 1)
Diseases named in the same sentence as CHEK1 in open-access papers (continued):
Sharing a sentence is not in itself a finding about the gene and the disease.
tumor (continued). "Also using PARPi synergy with the ICIs in tumours with homologous recombination damage reported increases in the mutational load in tumour cells and increased expression of PD-L1 by ATM-ATR-Checkpoint kinase 1 pathway." (PMID 36845691, 2023). "We find that JQ1 suppresses MYC transcription and can synergize with CHEK1 inhibitor prexasertib to suppress tumor growth more effectively than either single agent alone, while prolonging survival in the animals bearing CTDNEP1-deficient MYC-amplified MB tumors." (PMID 36765089, 2023). "In addition, we showed that CDK1/PBK/CHEK1 overexpression promotes GBM tumor aggressiveness, immunosuppression, and progression by recruiting the tumor-promoting immune cells such as the T Cells CD4+ Th2 subtype, MDSCs, and the TAM-M2 subtype." (PMID 38003585, 2023). "In contrast, both CHEK1 and PAX8 appear to associate positively with PDAC aggressiveness and poor prognosis, based on the deleterious effects of their elevated expression in tumor grade progression and overall survival." (PMID 36831395, 2023). "Checkpoint kinase 1 (CHK1) is a master modulator of the DNA damage response that controls cell cycle progression, DNA damage repair, and DNA replication, dampening excessive DNA damage and boosting the tumor cells’ overall survival fitness." (PMID 35887326, 2022). "Specifically, the inhibition of DBF4, CCNA2, CCNB1, MCM6, CDC45, CHEK1, and CDC6 may be implicated in KCNQ1-mediated tumor suppression." (PMID 35216393, 2022). "The correlation of CHEK1 expression with the tumor grade and disease recurrence has also been reported, suggesting a role in tumor development, which may be a result of its regulatory role in the circadian rhythm." (PMID 35993051, 2022). "The results exhibited that CHEK1 was remarkably highly-expressed in the tumor samples." (PMID 35428780, 2022). "Utilising Checkpoint Kinase 1 (Chk1) inhibitors to increase cytoplasmic DNA may be a potential strategy to increase the sensitivity of tumours to immune checkpoint modulators." (PMID 35006469, 2021). "Furthermore, histological analyses of primary tumours obtained from CRC xenograft mice revealed that miltefosine treatment reduced the expression of both CHEK1 and CD44." (PMID 34841679, 2021). "Besides, the ATR–CHEK1 pathway is often upregulated in human neoplasms, especially CHEK1, whose promoter activity is believed to promote tumor growth." (PMID 33800556, 2021). "Overexpression of DNA repair proteins such as PARP1, checkpoint kinase 1 (Chk1), and enhancer of zeste two polycomb repressive complex two subunit (EZH2) are independent of DNA-level mutations, but significantly contribute to tumor growth." (PMID 34531756, 2021). "CHEK1 is regarded as a target gene for potential tumor treatment." (PMID 32391047, 2020). "Under several circumstances CHEK1 promotes tumor growth and increases therapy resistance." (PMID 31652257, 2019). "Due to its anti-injury effect, CHEK1 plays an important role in tumor development and apoptosis." (PMID 30228980, 2018). "Importantly, ATR and CHEK1 expression were both inhibited in the tumor tissues of miR-126 overexpression group mice." (PMID 30315225, 2018). "Of these patients, tumor expression of miR-195 and CHEK1 were analyzed in 85 and 276, respectively." (PMID 25840419, 2015). "Taken together, we speculate that reducing CHEK1 activity and increasing miR-195 expression work in concert suppressing tumor growth." (PMID 25840419, 2015). "Increased levels of CHEK1 in tumour cells may therefore provide them with a survival advantage due to the ability to tolerate a higher level of DNA damage and the tumour cells thereby become chemotherapy resistant." (PMID 25881228, 2015). "Concomitant with the increased nuclear staining of hRad9, Maniwa's group demonstrated an increase in phosphorylated checkpoint kinase-1 (ChK1), suggesting that this is a physiologic response of the DNA damage checkpoint signaling pathway to genetic aberrations that occur in tumor cells." (PMID 18616832, 2008).
tumor (continued). "Tumor cells with underlying defects in genome maintenance, such as FBXO7 deficiency, are hypothesized to be particularly reliant on CHEK1 function for survival, making CHEK1 inhibition an attractive SL strategy in this context." (PMID 40896366, 2025). "Therefore, we analyzed the correlation between tumor mutation burden and the expression of targets, and the results showed that the expression of AURKA, CCNA2, CCNE1, CDK1, CHEK1, and PLK1 were significantly positively correlated with the tumor mutation burden." (PMID 36483630, 2022). "Thus the reduction of RAD23A with longevity could inhibit CHEK1 degredation and allow promotion of tumor growth and therapy resistance." (PMID 31652257, 2019). "On the other hand, the recent report of a remarkable and possibly curative response to the CHEK1 and CHEK2 (CHEK1/2) inhibitor AZD7762 in a small-cell tumor with RAD50 mutation illustrates what is possible when a targeted therapy is given to a susceptible tumor." (PMID 26437225, 2015). "Notably, significant functional differences are predicted between the long or short isoforms of TCF12, OSBPL1A, TRAK1, CHEK1, ANK3, LMO7 and SCIN indicating that the observed tumor associated changes in TSS usage probably have an impact on the growth properties of the neoplastic cells." (PMID 21999571, 2011). "Multiplexed immunofluorescence revealed that CHEK1 and MIF are co-expressed in tumor cells, and CHEK1-high tumor cells exhibit closer spatial proximity to M2-like macrophages." (PMID 41722056, 2026). "A heatmap of the 11 mRNA expression levels of the tumor samples displayed that the seven genes, including CCNB1, CCNB2, CHEK1, FEN1, PTTG1, RACGAP1, and UBE2C, had higher expression levels in the tumor tissue." (PMID 41009526, 2025). "Specifically, PIWIL4, SATB1, GSE1, NCOR1, SAP30L, ATM, and BMI1 were significantly downregulated in tumor tissues relative to normal controls, while BUB1, CHEK1, MASTL, DNAJC2, UBE2D1, and SSRP1 showed pronounced upregulation." (PMID 41208974, 2025). "In human tumours, a robust positive correlation was discerned between NCAPH expression and proliferation markers (Ki67) or genomic instability markers (H2AX and CHEK1)." (PMID 38344872, 2024). "The activity of checkpoint kinase 1 (CHK1) promotes the transcription of CIP2A/p90, thereby inhibiting the activity of PP2A, the tumor suppressor." (PMID 36911405, 2023). "We found that CDK1/PBK/CHEK1 overexpression drives the cell cycle, subsequently promoting GBM tumor progression." (PMID 38003585, 2023). "There was a moderate positive correlation between tumor purity and CDK1/PBK/CHEK1 with a Rho of 0.474, 0.459, and 0.513." (PMID 38003585, 2023). "The simultaneous inhibition of CDK1/PBK/CHEK1 will promote the cell cycle arrest, senescence, and apoptosis of GBM, suppressing tumor progression." (PMID 38003585, 2023). "The correlation between CHEK1, CDC25A, FOXK1 and tumor-infiltrating immune cells in the LIHC microenvironment was evaluated by using TIMER." (PMID 35309118, 2022). "When molecular cascades featuring the homologous repair system are operating, checkpoint kinase 1 (Chk1) activation can also trigger the STAT1 – STAT3 – IRF1 signaling pathway, inducing PD-L1 expression in tumor cells." (PMID 35211121, 2022).
tumor (continued). "A study combining olaparib and the CHK1 (checkpoint kinase 1) inhibitor prexasertib in a small group of patients, identified partial response in some HGSOC patients with BRCA1 mutant tumours who had demonstrated PARPi resistance." (PMID 36230543, 2022). "In terms of immune microenvironment, we found that the expressions of AURKA, CCNA2, CCNE1, CDK1, CHEK1, and PLK1 were negatively correlated with tumor immune infiltrating cells." (PMID 36483630, 2022). "Subgroup U-II was more related to tumor proliferation, including cell cycle (MCM2, ANAPC4, CHEK1, etc.), RNA splicing, and DNA repair." (PMID 35659036, 2022). "The role of hsa-miR-508-5p upstream of IGF1, CHEK1 and CCNB1 in IDD remains to be explored, but it has been extensively studied in various tumour tissues and cardiovascular." (PMID 36175893, 2022). "In addition, silencing of CHEK1 in vivo could effectively decrease tumor size in nude mice." (PMID 35428780, 2022). "The correlation between the expression of cell cycle-related genes and immune cells suggested roles for CDK4, CCNB1, CHEK1 and CDKN2A in regulating HCC tumor immunology." (PMID 36403263, 2022). "We then examined the expression of 9 model genes in single cells and found that CDK1, AURKB, CCNA2, and CHEK1 are mainly expressed in CD4 cells, while PRKAA2, CDK5, and PRKCD are mainly expressed in tumor cells." (PMID 36120466, 2022). "In addition, we found that the expressions of AURKA, CCNA2, CCNE1, CDK1, CHEK1, and PLK1 were all positively correlated with TMB, which was consistent with previous research results, and there was a positive correlation between tumor dryness and tumor mutation burden." (PMID 36483630, 2022). "Specifically, the inhibition of checkpoint kinase 1 (CHEK1) overcame carboplatin resistance both in vitro and in a pre-clinical carboplatin-resistant patient-derived tumor xenograft (PDX) model." (PMID 33542435, 2021). "Based on the action mechanism of miRNA on mRNA and putative oncogenic roles of CELSR3, GPSM2, and CHEK1, potential miRNAs should be tumor suppressive miRNAs and should be negatively correlated with CELSR3, GPSM2, or CHEK1." (PMID 32257949, 2020). "The expression of PLK1 and CHEK1 was significantly higher in tumor tissues than in normal tissues, whereas WEE1 expression was significantly lower in tumor tissues than that in normal tissues." (PMID 31387297, 2019). "With regards to their functions, CHEK1, RAD51 and CDC25A have been suggested to promote tumor development, while GADD45A can act as a tumor suppressor." (PMID 30042885, 2018). "For instance, recent studies also showed that combined inhibition of checkpoint kinase 1 (CHK1), another inducer of G2/M phase arrest, and WEE1 increased therapeutic efficacy and reduced tumor growth." (PMID 27616351, 2016). "Surprisingly, that study also showed that let-7 represses several tumour suppressor genes (BRCA1, BRCA2, FANCD2, and PLAGL1, among others) and checkpoint regulators (CHEK1, BUB1, BUB1B, MAD2L1, and CDC23, among others)." (PMID 20179807, 2010). "The heat map shows that genes such as CHEK1, PIK3CD, and PYGL are upregulated in tumor tissues." (PMID 40699827, 2025). "In previous studies, a combination of checkpoint kinase 1 inhibitor (CHK1i) and low-dose hydroxyurea (LDHU) has been shown to have tumour-selective toxicity, targeting tumours with elevated levels of replication stress without significant toxicity in normal tissue." (PMID 40507298, 2025). "Subtype stratification analysis revealed a significant correlation between tumor mutational burden (TMB) and CHEK1 expression in LumA/LumB, but not in TNBC." (PMID 40344565, 2025). "Since tumor cells are under constant oncogenic stress, they become addicted to checkpoint signals arising from kinases such as ATR (Ataxia Telangiectasia and Rad3-related protein), Chk1 (checkpoint kinase 1) and Wee1." (PMID 40628724, 2025).
tumor (continued). "In addition, the results show that CKS2, PCNA, CHEK1, and NCAPG2 are also involved in the regulation of tumor DNA replication and mismatch repair." (PMID 38937855, 2024). "The mRNA expression levels of KRAS, ATR, CHEK1 genes in EC tissue samples from both groups with and without recurrence were independent of the depth of tumor invasion into the myometrium." (PMID 38669256, 2024). "Although targeted inhibition of CHEK1 with prexasertib monotherapy showed no considerable tumor regression effect, combining prexasertib with cisplatin significantly reduced the tumor volume compared with cisplatin monotherapy." (PMID 38994959, 2024). "CHEK1 was also used in zhang's study as a hub gene and new biomarker for IDD, a serine/threonine-specific protein kinase that regulates the DNA damage response and cell cycle checkpoint response and influences tumour development through both of these." (PMID 36175893, 2022). "Depletion of MCM6 abolished GC tumor growth and sensitized GC to standard cytotoxic treatments via suppression of the DNA damage-induced ataxia telangiectasia and rad3-related protein/checkpoint kinase 1 (ATR/Chk1) signaling." (PMID 36185598, 2022). "Interestingly, the tumor suppressor candidates on 11q23 include; ATM, CHEK1 and H2AFX, all of which coalesce within the same DNA damage response pathways, which have been shown to be active at the G1 restriction checkpoint." (PMID 32312269, 2020). "In vitro and in vivo (on patient-derived xenograft mice models) studies revealed an extensive activity of the other potent CHEK1 (and CHEK2) inhibitor prexasertib in HGSOC, both as a monotherapy and in combination with PARPi olaparib, with anti-tumor activity even in olaparib-resistant models." (PMID 32605254, 2020). "Notably, the expression levels of CHEK1, PIK3CA, and PIK3CD were significantly increased in both the primary tumor tissues and xenografts." (PMID 32610557, 2020). "In this study we have also shown that CHRNA5 RNAi might result in reduced DNA damage response (DDR) based on TCGA and METABRIC tumor data, and GSEA and DAVID functional analyses as well as quantification of total and phosphorylated CHEK1 protein levels." (PMID 30543688, 2018). "The relative expressions of CCNB1, CCNB2, and CHEK1 mRNA were 3.938±3.887-, 3.225±3.388-, and 3.186±3.508-fold upregulated in 20 tumor tissues versus adjacent nontumor tissues, respectively." (PMID 30228980, 2018). "CHEK1 expression was slightly higher in tumor than in adjacent non-tumor tissues, but the difference was not statistically significant (p = 0.832) (Data not shown)." (PMID 25840419, 2015). "Here we did not observe differences in CHEK1 expression levels among resistant and sensitive tumours." (PMID 25881228, 2015). "High expression of Chek1, Chek2 and MCM3 has previously been demonstrated to be associated with a poor prognosis in the here studied cohort of tumours, although not independent of other established clinicopathological parameters." (PMID 22284433, 2012). "Here the CHEK2 gene was overexpressed (not enough tissue to examine protein expression), and the Chk1 (checkpoint kinase 1) protein, encoded by the CHEK1 gene increased its staining from below 5% to 50% of the tumour cells after resistance." (PMID 22905093, 2012). "Therefore, we suggest the upregulation of genes in our model work together in regulating cell cycle and tumor progression, with HJURP ensuring chromosome stability, CDK1 driving mitotic entry, and FOXM1 promoting proliferation and CHEK1 supporting cell survival under DNA damage conditions." (PMID 40299539, 2025).
tumor (continued). "Moreover, protein expression analysis indicated that although ATR is not differentially expressed in PDAC, tumor cells exhibit significantly higher CHEK1 levels than normal tissue." (PMID 39838187, 2025). "Moreover, in several systematic reviews, there are no documented germline CHEK1 mutations in PDAC, showing that it is extremely uncommon as a heritable susceptibility gene in this type of tumor." (PMID 41374970, 2025). "Identification of Core Targets: Five critical anti-GC targets (CDK1, CCNA2, TOP2A, CHEK1, and PLK1) were identified, with a focus on their roles in cell cycle regulation and chemotherapy resistance, providing mechanistic insights into Diosgenin’s anti-tumor effects." (PMID 40487391, 2025). "Moreover, the use of synthetic lethality extends to exploring combinations such as WEE1 G2 checkpoint kinase (Wee1) and checkpoint kinase 1 (CHK1) inhibitors in neuroendocrine prostate cancer (NEPC), with preclinical mouse models showing effective tumor growth inhibition." (PMID 39204153, 2024). "Importantly, LOH of CTDNEP1 in the tumor may increase the therapeutic window for combined treatment with MYC and CHEK1 inhibition." (PMID 36765089, 2023). "Likewise, ATF2, CHEK1, DCAF8, and PAX8 showed diverse expression across the different tumor grades." (PMID 36831395, 2023). "The overlap with differentially expressed genes in tumor versus normal breast tissues identified a subset of 24 genes, 4 of which associated to the highest negative prognostic impact in BC (KHDRBS1, EXO1, CHEK1, BARD1)." (PMID 35217791, 2022). "Furthermore, the levels of ATR and CHEK1 mRNA were upregulated in tumor tissues compared to non-tumor tissues in the TCGA database (n = 50) and the GSE14520 cohort (n = 213)." (PMID 34663432, 2021). "Collectively, these data suggest that miR-497 may regulate proliferation, survival and tumor vascular permeability by targeting key genes involved in DDR such as WEE1 and CHEK1, cell growth and viability such as AKT3 and BCL2 and angiogenesis regulators such as VEGFA." (PMID 26824183, 2016). "Unlike CHEK2, the T-cell compartment associated with the low CHEK1 expressing tumor cells showed no significant enrichment for “Interferon γ (IFN-γ) signaling” (p = 0.76) and “T-cell-mediated cytotoxicity pathway” (p = 0.18) as compared to the T cells from high CHEK1 expressing tumor cells." (PMID 36949040, 2023). "Interestingly, from these 17 significant pairs (adjusted p-value ≤ 0.05) several downregulated tumour-suppressor miRNAs (e.g., miR-let-7c, miR-139, miR-145 or miR-195) appeared to regulate oncogenic genes related to the cell cycle and DDR pathways (BUB1B, AURKA, BIRC5, CENPK, BRCA1 and CHEK1)." (PMID 28387377, 2017). "Here again, if we query cancer datasets, CHEK1/CDK being cell-cycle regulators, are seen overexpressed in most aggressive tumours (e.g. triple-negative breast cancers), and but are not necessarily mutually exclusive to MYC overexpression." (PMID 26427375, 2015). "The relative expression levels of CDKN3, MKI67, CEP55, SPAG5, AURKA, TOP2A were consistent with the results of bioinformatics analysis (P < 0.05), while the expression levels of UBE2C, CHEK1 and BIRC5 in tumor samples were not significantly different from adjacent normal samples." (PMID 35178291, 2022). "We found that the expression levels of UBE2C, CHEK1, and BIRC5 in tumor samples were not significantly different from adjacent normal samples, which may be due to the small sample size." (PMID 35178291, 2022).